ALB (albumin)
Diseases named in the same sentence as ALB in open-access papers (continued):
Sharing a sentence is not in itself a finding about the gene and the disease.
malnutrition (continued). "Multivariate analysis showed that GLIM-defined malnutrition plus low hand-grip strength, low albumin, and combined organ resection were independent risk factors for postoperative complications." (PMID 38395798, 2024). "Hypoalbuminemia, defined by the serum albumin less than 35 g/l, is associated with malnutrition, cirrhosis and nephrotic syndrome, with a prevalence of about 3% in pregnant women." (PMID 38173765, 2024). "Low serum ALB is linked to higher mortality risk across both time frames, indicating that malnutrition adversely affects both short-term and long-term survival." (PMID 39080581, 2024). "High levels of CRP indicate the need for monitoring potential aspiration pneumonia, while low levels of ALB suggest a risk of malnutrition in dysphagia patients." (PMID 38993239, 2024). "Malnutrition and low serum albumin were also identified as significant risk factors for mid-term morbidity in the adjusted model." (PMID 38436719, 2024). "Common biochemical markers that physicians considered in relation to nutrition risk and malnutrition included albumin and prealbumin." (PMID 39064658, 2024). "Clinically, low albumin levels are often associated with chronic liver disease, malnutrition, and tumors, among others." (PMID 39678198, 2024). "Low albumin levels can signify inflammation, malnutrition, or protein loss, factors that elevate thrombosis risk." (PMID 39839389, 2024). "Although the role of serum ALB in the assessment of nutritional status has been recently challenged, studies have shown that patients with low serum ALB levels are at risk of malnutrition." (PMID 38974687, 2024). "In contrast, peripheral albumin level sensitively reflects the nutrition status of the body; a low albumin causes a high level of malnutrition and is related to poor clinical outcomes for lung cancer patients." (PMID 39108262, 2024). "Vitamin D, serum lab values including albumin, and iron deficiency anemia, and nutritional diagnoses such as sarcopenia or malnutrition are the main topics in previous publications in relation to nonunion specifically." (PMID 39518692, 2024). "Historically, biochemical markers such as albumin were considered to have a positive diagnostic value for malnutrition." (PMID 38817798, 2024). "Albumin levels from the last 4 weeks of a patient’s life had been excluded to reduce the contribution of other causes for hypoalbuminemia, such as malnutrition." (PMID 39199595, 2024). "Lower levels of albumin indicate malnutrition or are associated with the inflammatory processes that inhibit albumin production or increase albumin consumption." (PMID 38707705, 2024). "As a result, higher CRP levels, and hence immunological activation, are associated with lower serum albumin levels: a clear sign of defective immunity, exacerbated inflammation, and malnutrition." (PMID 38975012, 2024). "Both inflammation and malnutrition risk have been associated with low albumin levels and lymphocyte counts." (PMID 39398776, 2024). "Low albumin levels can result from various factors, including underlying medical conditions, liver disease, kidney problems, inflammation, malnutrition, and medication use." (PMID 38528491, 2024). "In our review, malnutrition status was measured using weight loss, BMI, albumin or hemoglobin levels, and muscle or fat mass." (PMID 39061235, 2024). "Albumin level reflects nutritional status, and a decrease in this factor indicates that the patient is in a state of malnutrition, which is a risk factor influencing prognosis." (PMID 39403382, 2024). "In our study, albumin and prealbumin deficiencies were shown to indicate the risk of malnutrition related to inflammation in patients with childhood cancer." (PMID 39619813, 2024). "Albumin levels, commonly used as a marker of nutritional status, are independently associated with mortality in HD patients, reflecting both malnutrition and inflammation." (PMID 39337040, 2024).
malnutrition (continued). "The possible reason for the lower albumin result is due to a combined effect of hypovolemia and malnutrition in HG, potentially linked to vomiting severity." (PMID 39741505, 2024). "The analysis revealed lower albumin levels (Rho = -0.235, p < 0.001), higher urea levels, increased use of antibiotics, and a higher risk of malnutrition, as indicated by the NRS (Rho 0.219, p < 0.001)." (PMID 38910242, 2024). "The Geriatric Nutritional Risk Index (GNRI) is a newer risk index that measures malnutrition in elderly patients by using serum albumin and patients’ ideal body weight." (PMID 38983939, 2024). "Several modifiable predisposing risk factors were identified, such as frailty, malnutrition, low albumin concentration, anticholinergic drug burden related to polypharmacy, and preoperative anemia." (PMID 39144259, 2024). "Serum albumin levels are closely associated with malnutrition and are independent predictors of inflammation and mortality." (PMID 38802494, 2024). "Low levels of albumin can be associated with malnutrition and cachexia (severe weight loss and muscle wasting) and be related with inflammatory response in the body, which are common in advanced cancer patients." (PMID 39372874, 2024). "Studies have also demonstrated that low albumin levels, associated with malnutrition, can heighten the risk of adverse outcomes." (PMID 39734672, 2024). "The results of this study also showed that low hemoglobin, prealbumin, serum albumin and total protein were independent risk factors for malnutrition in SPBP, consisted with a previous study." (PMID 38694222, 2024). "Preoperative nutritional status has been suggested as a potential predictor of postoperative outcomes, with low serum albumin levels utilized as a marker of malnutrition and increased risk of postoperative complications." (PMID 38707022, 2024). "In patients with lung nodules, low albumin levels can be caused by malnutrition, impaired liver function, tumor metastasis, digestive tract tumors, liver tumors, and other factors." (PMID 40103669, 2024). "The findings revealed a statistically significant correlation between serum ALB levels and malnutrition (OR = 0.90, 95% CI: 0.85–0.96, p < 0.001), suggesting that higher ALB levels are associated with a reduced risk of malnutrition." (PMID 39040927, 2024). "A reduction in serum albumin levels can thus obstruct nutrient transport and conversion, leading to substantial nutritional deficits and heightened malnutrition risk." (PMID 39040927, 2024). "At the same time, albumin andlymphocyte count are also closely related to the occurrence of sarcopenia, acommon complication caused by malnutrition." (PMID 39076344, 2024). "Higher baseline PS and HGS levels were correlated with younger age, female sex, elevated serum creatinine, eGFR, serum phosphorus, serum albumin levels, and a lower risk of malnutrition." (PMID 38698329, 2024). "In a multivariate logistic regression, the associations were confirmed for waist circumference and albumin, with high values of these variables being inconsistent with malnutrition." (PMID 39683376, 2024). "Nutritional deficiency can reduce albumin synthesis in the liver, compromising its levels and functions." (PMID 39480760, 2024). "Albumin is a protein that maintains fluid balance and osmolality in bloodstream and it is associated with malnutrition and problems in intake of nutrients in the gut." (PMID 36897911, 2023). "GLIM diagnosed that malnutrition was significantly associated with age, BMI, hand grip strength, albumin, total protein, hemoglobin, lymphocyte count, total bilirubin, alanine transaminase, and platelet count." (PMID 36917167, 2023). "And for malnutrition, about thirteen tools were mentioned, besides which, BMI only and BMI with albumin were considered to be diagnostic criteria in three articles." (PMID 36895271, 2023).
malnutrition (continued). "Predisposing risk factors such as MELD score, hyponatremia, serum bilirubin, and albumin and precipitating risk factors such as DM, malnutrition, sarcopenia, and a more advanced age can predict HE." (PMID 37109068, 2023). "A major consequence is maldigestion resulting in malabsorption, malnutrition, and the ensuing nutritional deficiencies (including albumin, pre-albumin, transferrin, lipoproteins, fat soluble vitamins, calcium, magnesium, zinc, thiamine, and folic acid)." (PMID 37958314, 2023). "Nevertheless, the fact that low albumin has been associated with infections, vascular complications, and organ dysfunction is in concordance with immune dysregulation from malnutrition." (PMID 36811703, 2023). "In fact, reduced serum albumin levels are observed in diseases associated with malnutrition, while high serum albumin levels are associated with metabolic syndrome, an indicator of obesity and overeating." (PMID 37627906, 2023). "PD patients are at high risk of malnutrition, and serum albumin is commonly used as a marker of nutritional status." (PMID 38021540, 2023). "Malnutrition, especially preoperative malnutrition and low albumin levels (<3.0 g/dL), increases the risk." (PMID 38074035, 2023). "Another mechanism that explains the association between albumin and malnutrition in patients with kidney disease is that albumin possesses anti-inflammatory and antioxidant properties." (PMID 37250638, 2023). "The results showed that higher PLR was significantly associated with lower BMI, hemoglobin, and albumin levels, indicating preoperative malnutrition." (PMID 37237259, 2023). "CONUT utilizes n total peripheral lymphocytes, serum albumin, and total cholesterol to categorize hospitalized patients as low, medium, or high risk for malnutrition." (PMID 36904295, 2023). "A previous study suggested that the serum albumin level reflected malnutrition and protein loss caused by catabolism and inflammation." (PMID 36595498, 2023). "The geriatric nutritional risk index (GNRI) assesses malnutrition using the patient’s ideal weight, actual weight, and serum albumin." (PMID 36839241, 2023). "Since malnutrition is a risk factor for sarcopenia, the improvement in serum albumin (a marker of nutritional status) is believed to contribute to reducing the risk of sarcopenia, similar to the changes observed in muscles." (PMID 37513691, 2023). "Another study of older adults showed that age, drinking, chronic diseases, depression, BMI, ADLs & IADLs, number of recent falls, cognitive impairment, insomnia, low hemoglobin and albumin levels were independently associated with malnutrition." (PMID 38260073, 2023). "Older adults are more likely to have diseases or malnutrition, thus increasing the risk of low albumin levels." (PMID 37947552, 2023). "Serum albumin has consistently been used as an indicator of malnutrition, and hypoalbuminemia is associated with immune dysfunction and systemic inflammation." (PMID 38112846, 2023). "Low albumin levels are associated with poor liver function, and patients with advanced cancer were reported to display a high incidence of malnutrition due to cancer cachexia and cancer-associated bleeding." (PMID 37251954, 2023). "Albumin is synthesized in the liver, and low albumin levels are often associated with malnutrition and tumor progression." (PMID 37143476, 2023). "Hypoalbuminemia occurs in several diseases, including malabsorption and malnutrition, renal disease, where the loss of albumin occurs across the glomerulus (e.g., nephrotic syndrome), or hepatic diseases, where there is inadequate albumin synthesis." (PMID 37887077, 2023). "Although traditionally considered to be an indicator of malnutrition, albumin is a multifunctional protein associated with DM, inflammation, and thrombosis, which are risk factors for or triggers of STEMI or its progression." (PMID 37745131, 2023).
malnutrition (continued). "It has been shown that low albumin levels are associated with anemia and that anemic patients have an increased risk of hypoalbuminemia, which is further enhanced in malnutrition patients." (PMID 37034317, 2023). "Low albumin levels, a marker of inflammation and malnutrition, have increased susceptibility to death in dialysis patients." (PMID 37221481, 2023). "This study aimed to evaluate blood biomarkers (serum albumin, TP and Hgb) and their correlation with malnutrition and to identify factors associated with blood biomarkers alteration among adult patients with cancer on treatment follow up." (PMID 36869395, 2023). "The results showed that hemoglobin and albumin levels, malnutrition, and fall risk were closely related." (PMID 37559927, 2023). "Albumin, the most abundant plasma protein with highly susceptible targets for post-translational modifications, not only reflects aspects of malnutrition status (such as anemia), but is also related to DM because of the associated glycation." (PMID 37745131, 2023). "In terms of the predictive value of the NLR, it is important to consider the potential association between inflammation and malnutrition, as well as protein-energy wasting, with lymphocytes and serum albumin levels allowing evaluation of nutritional status." (PMID 37791567, 2023). "Low levels of hemoglobin and albumin are considered indicators of malnutrition, and both were also associated with FTR, once again demonstrating the fragility of these patients." (PMID 37971027, 2023). "Low albumin levels in patients receiving HD or peritoneal dialysis can lead to high all-cause mortality, which is related to malnutrition." (PMID 37784041, 2023). "Meanwhile, fibrinogen is a long-acting plasma acute-phase reactant, and the change in albumin level has been attributed to the changes in nutritional status; furthermore, hypoalbuminemia represents a chronic inflammatory state caused by malnutrition." (PMID 36909340, 2023). "Albumin is an important indicator reflecting protein deficiency and malnutrition, while lymphocytes are strongly relevant to patients’ immune status." (PMID 37867496, 2023). "As we all know, albumin plays an important role in the homeostasis of the body, and hypoproteinemia, as a sign of malnutrition, is a consequence of suppressed or increased loss." (PMID 38375202, 2023). "Low albumin level has been used as a marker of malnutrition related to increased risk of adverse health outcomes, including death and other severe diseases." (PMID 37957767, 2023). "Similar to albumin, transthyretin is a marker of inflammation-related nutritional risk, a key component of malnutrition related to acute or chronic disease." (PMID 36891188, 2023). "One study reported that higher SARC-F scores were associated with moderate or severe malnutrition, as categorized using the controlling nutritional status score that is calculated from serum albumin level, total lymphocyte count, and total cholesterol level." (PMID 36890183, 2023). "The identified critical risk factors for malnutrition in this cohort were body mass index, albumin, impairment in activities of daily living, dietary habits, and glycosylated hemoglobin." (PMID 37715131, 2023). "In the present study, a small number with weight loss aged 70 were at risk of malnutrition with a low serum albumin level, low protein energy ratio, and low animal protein energy ratio." (PMID 37149581, 2023). "The logistic regression analyses revealed that albumin, prealbumin, lactate dehydrogenase, alkaline phosphatase, ascites, and sarcopenia were influencing factors for malnutrition risk." (PMID 36849719, 2023). "Malnutrition (BMI and albumin) significantly affects all-cause and cardiovascular mortality in MHD patients, and malnutrition and inflammation reinforce each other." (PMID 36792978, 2023).
malnutrition (continued). "Low albumin levels are associated with malnutrition and inflammation, whereas low globulin levels are associated with chronic inflammation and indicate cumulative exposure to various pro-inflammatory cytokines." (PMID 35601226, 2022). "A decrease in plasma ALB is purportedly associated with the incidence of malnutrition and renal impairment; while an increase in GLB level is related to chronic inflammation." (PMID 35544959, 2022). "We found that malnutrition indicators consisted of erythrocyte, hemoglobin, serum albumin and total protein associated with AD cognitive scores most, as well as FT3, which is consistent with previous study." (PMID 35265656, 2022). "For example, we would expect albumin to be low in situations where there is poor synthesis in liver disease, reduced intake in malnutrition, albumin loss in renal and gastrointestinal disease, and loss through increased vascular permeability in sepsis." (PMID 35268297, 2022). "Meanwhile, 3 reviews of low to high quality demonstrated that masticatory problems, which have been identified as independent predictors for low BMI and serum albumin level, weight loss and protein-energy malnutrition, are also key for malnutrition." (PMID 36388333, 2022). "Age, Child-Pugh class C, albumin level, vitamin D deficiency, male gender, and alcoholic etiology were significantly associated with malnutrition." (PMID 35453941, 2022). "Inflammation and malnutrition both decrease the rate of albumin synthesis, whereas inflammation is also associated with increased albumin catabolism and influences albumin distribution between the vascular and extravascular components." (PMID 35398717, 2022). "Intestinal microecological homeostasis was disrupted, and the rats exhibited signs of malnutrition, such as weight loss and decreased serum albumin and transferrin levels." (PMID 36458537, 2022). "Malnutrition, for example, can manifest itself both in a decreased albumin level and, in the case of pronounced substrate deficiency, in anemia." (PMID 35574347, 2022). "Previous studies have shown that there is interaction between inflammation and malnutrition, while severe systemic inflammatory reactions can impair albumin synthesis and lead to malnutrition and weight loss." (PMID 35587595, 2022). "In the present study, a diagnosis of malnutrition was made if patients met one of the following criteria: body weight loss >5% in 6 months, weight loss >2% and BMI <20 kg/m2, or serum albumin level below the normal lower limit." (PMID 35191609, 2022). "We found that albumin levels were statistically significantly lower in patients who were at a risk of malnutrition, in accordance with the NRS 2002, than in those with a BMI > 18.5 kg/m2 and averaged 2.43 g/dL." (PMID 35627363, 2022). "The waist circumference is negatively correlated with nutritional markers, such as the albumin and pre-albumin levels; patients with a larger waist circumference are at risk for malnutrition, promoting cognitive frailty." (PMID 35366144, 2022). "In the univariate analysis for the length of postoperative hospital stay in surgical inpatients, the associated factors were serum albumin, hemoglobin, primary tumor site, tumor risk stratification, and malnutrition risk classified by NRS2002." (PMID 35479752, 2022). "In our multivariate logistic regression model, gender, age, weight loss, reduced food intake, and serum ALB expression were independently associated with malnutrition in patients with chronic kidney disease." (PMID 36687720, 2022). "Serum albumin level is one of the major risk scores for estimating malnutrition, while triglycerides can also reflect the nutrient situation of heart failure patients before transplantation." (PMID 35669472, 2022). "Albumin is produced by the liver, but it is known that it is also affected by several other causes such as chronic illness, heart failure, and malnutrition." (PMID 36013063, 2022).